RAB1B (RAB1B, member RAS oncogene family)
Diseases named in the same sentence as RAB1B in open-access papers (continued):
Sharing a sentence is not in itself a finding about the gene and the disease.
infection (10 papers, 2014 to 2024). The state of being infected such as from the introduction of a foreign agent such as serum, vaccine, antigenic substance or organism. "At 20 min post-infection, Lamp1 associated with ~55% of YCVs in Rab1b siRNA treated cells, and was maintained at this elevated level at 80 min post-infection." (PMID 26495854, 2015). "During the infection of macrophages by Yersinia pestis, Rab1b recruitment to the Yersinia-containing vacuole directly inhibits phagosome maturation; active Rab1b stabilizes Arf1 on Golgi membranes, and Rab1b is required for GBF1 membrane association." (PMID 38169281, 2024). "During an early stage of infection, Rab4 cooperates with Rab1b to inhibit the fusion of YCVs with lysosomes." (PMID 33499114, 2021). "It has been demonstrated that Rab1b is recruited to the PV at later infection stages (6 h p.i.)and, interestingly, the knockdown of Rab1b altered the vacuole growth, indicating that this protein is required for a suitable biogenesis of the Coxiella PV." (PMID 27005665, 2016). "In contrast, we observed a significant increase in Lysotracker colocalization in macrophages treated with siRNA targeting Rab1b at both 20 and 80 min post-infection (p≤0.01 and P≤0.001, respectively)." (PMID 26495854, 2015). "Specifically, we have demonstrated that Y. pestis recruits Rab1b to the YCV during infection of macrophages and that this GTPase is required for intracellular survival." (PMID 26495854, 2015). "This analysis revealed that intracellular bacterial numbers for both strains were significantly decreased in Rab1b treated cells as early as 2 h post-infection, which is the earliest time point we can monitor after gentamicin removal (p≤0.001)." (PMID 26495854, 2015). "We also monitored Y. pestis intracellular bioluminescence temporally over the course of the infection to determine how early during infection Y. pestis intracellular survival was impacted by Rab1b knockdown." (PMID 26495854, 2015). "The ability of Y. pestis to inhibit YCV acidification was greatly attenuated in Rab1b knocked down cells, where ~70% of the bacteria were observed within acidified vacuoles within 20 min post-infection (p≤0.01)." (PMID 26495854, 2015). "We observed a difference in Y. pestis intracellular numbers in Rab1b siRNA treated cells within 2 h of macrophage infection." (PMID 26495854, 2015). "Previous studies with L. pneumophila demonstrate the cyclic recruitment and release of Rab1b on the LCV within 2 hours post-infection." (PMID 26495854, 2015). "Macrophages were fixed 1 hr after infection and Rab1b staining was used to assess the function of DrrA." (PMID 24992562, 2014). "Importantly, the data suggests that ubiquitin, annexin A1, annexin A2, MavP are putative novel interaction partners and that Rab1A, Rab1B, Rab6, and Rab10 are the predominant Rab GTPases targeted by SidM during infection." (PMID 26755725, 2016). "Furthermore, Y. pestis remained within acidified vacuoles in Rab1b siRNA treated macrophages at 80 min post-infection." (PMID 26495854, 2015). "However, Rab1b may also be required for efficient phagocytosis and the difference in Y. pestis numbers at 2 h post-infection could be a result of less bacteria gaining entry into the macrophages prior to gentamicin treatment." (PMID 26495854, 2015). "Here, we show that S. aureus generates tubular structures marked with the small GTPases Rab1b and Rab7 and by the autophagic protein LC3 at early times post-infection." (PMID 29046869, 2017). "RAW264.7 macrophages were transfected with Rab1b siRNA and then treated with Lysotracker Red DND-99 prior to infection with Y. pestis CO92 pCD1(-) pGEN222, which constitutively expresses EGFP." (PMID 26495854, 2015). "Hence, we analyzed the infection-related localization of both, RAB1A and RAB1B, and detected a partial and a strong colocalization of RAB1A and RAB1B, respectively, with SIF." (PMID 32658937, 2020).
infection (continued). "To test this hypothesis, we transfected RAW264.7 macrophage cells with siRNA targeting Rab1b and treated transfected cells with Lysotracker Red DND-99 prior to infection with L. pneumophila to monitor LCV acidification." (PMID 26495854, 2015). "Together these data demonstrate that Rab1b is required for Yersinia intracellular survival, which is independent of the Ysc T3SS, and bacterial survival is impacted by Rab1b very early during the infection process." (PMID 26495854, 2015). "Since the YCV also expands late during infection (though not to the degree of these former pathogens) to form a spacious vacuole, it is possible that Rab1b may contribute to YCV expansion." (PMID 26495854, 2015). "While the PhoPQ two component regulator has been shown to contribute to intracellular survival, likely through the regulation of other genes, we speculate that these genes do not regulate survival through Rab1b because phoPQ mutants still inhibit YCV acidification during infection." (PMID 26495854, 2015).
tumor (10 papers, 2015 to 2025). "Together, these findings establish TBC1D22B as a regulator of ER‐to‐Golgi trafficking via RAB1B and implicate it in oncogenic transcriptional remodeling and tumor growth." (PMID 40878439, 2025). "The overexpression of Rab1B and MMP-9 in CRC tissues was associated with metastasis, advanced tumor stage, and poor OS." (PMID 37446127, 2023). "It is worth noting that increased expression levels of miR-135a led to a decrease in RAB1B expression and thus lower proliferation and invasion ability of the tumor cells." (PMID 32710726, 2020). "The high protein expression of Rab1B and MMP9 in 179 CRC tissues is associated with deep tumor invasion, lymph-node metastasis and advanced TNM stage." (PMID 28316326, 2017). "Further studies are required to decipher the molecular mechanism by which Rab1B interacts with MMP9 to promote tumor progression and metastasis in CRC." (PMID 28316326, 2017). "The current study employed stable cell lines in which sustained Rac1b overexpression was comparable to Rab1b upregulation in tumor tissues, and was therefore better suited for evaluation of cellular functions." (PMID 26918455, 2016). "Taken together, these data indicate the potential importance of RAB1B for the initiation or progression of different tumor types, although these roles need to be further clarified in future studies." (PMID 25970785, 2015). "The reported contradictory functions for Rab1B protein may be due to its distinct roles in a tissue origin- and tumor type-specific manner." (PMID 28316326, 2017). "Rab1B may participate in distinct signaling pathways, promoting either oncogenic or tumor-suppressing activity in different context." (PMID 28316326, 2017). "Taken together, our findings reveal that RAB1B acts as a metastasis suppressor in TNBC by regulating the TGF-β/SMAD signaling pathway and RAB1B may serve as a novel biomarker of prognosis and the response to anti-tumor therapeutics for patients with TNBC." (PMID 25970785, 2015). "Recently, it has been reported that RAB1B can be recruited by PITPNC1 to the Golgi apparatus, thus promoting the secretion of pro‐invasive and pro‐angiogenic factors and drive several tumor metastases." (PMID 36606322, 2023). "RAB1B (P<1E-12), RAB2A (P<1E-12), and RAB18 (P=2.7611E-09) were significantly up-regulated in primary tumor tissue (n=1 097) compared with that in normal tissue (n=114)." (PMID 32432324, 2020). "The protein expression of Rab1B and MMP9 in the paired CRC and non-tumor tissues was examined by immunohistochemistry (IHC)." (PMID 28316326, 2017). "Univariate analysis indicates that TNM stage, adjuvant chemotherapy, Rab1B and MMP9 proteins are significant predictors for OS and PFS of CRC patients (All P < 0.05), and Tumor depth is a marginally significant predictor for OS and PFS (P =0.065 and P =0.059, respectively)." (PMID 28316326, 2017).
myopathy (1 paper, 2022). A disease of the muscle in which the muscle fibers do not function properly. "Forty-six candidate genes are prioritized by multiple approaches (42 for LST and 6 for MVPA; 2 overlap) and point to endocytosis (CNIH2, RAB1B, KLC2, PACS1, REPS1, DNM3, EXOC4), locomotion (CADM2, KLC2) and myopathy (MLF2, HERC1, KLC2, SIL1) as relevant pathways." (PMID 36071172, 2022).
RAB1B also shares sentences with these, for which no sentence is quoted: amyotrophic lateral sclerosis (1 paper); cervical cancer (1); cholangiohepatoma (1); Intellectual disability (1); neurological disorders (1); non-small cell lung carcinoma (1); Parkinson disease (1); prostate carcinoma (1).